ELN (elastin)
Diseases named in the same sentence as ELN in open-access papers (continued):
Sharing a sentence is not in itself a finding about the gene and the disease.
fibrosis (17 papers, 2016 to 2026). the formation of excess fibrous connective tissue in an organ or tissue in a reparative or reactive process. "Macrophage accumulation in the aortic wall during angiotensin II infusion in mice is associated with fibrosis, elastin loss, and elevated blood pressure." (PMID 34717626, 2021). "Since elastin fibers are also accumulated in the lungs of bleomycin-induced fibrosis mice, so to assess the same, we performed a fastin elastin assay in Day 21 groups and controls and found that elastin levels are upregulated as compared to control mice." (PMID 37048117, 2023). "Fibrosis is a well-known pathological process in which several extracellular matrixes (ECMs), such as collagen, fibronectin, and elastin, accumulate abnormally in chronic inflamed and damaged tissues." (PMID 34594474, 2021). "High levels of other ECM proteins, such as elastin and fibronectin have been well documented in different murine models of chemically-induced fibrosis, including the NM-induced model." (PMID 32635192, 2020). "Enzymes belonging to the lysyl-oxidase (LOX) family are responsible for collagen as well as elastin crosslinking in pathological conditions like fibrosis." (PMID 32296422, 2020). "Fibrosis is characterized by the excessive deposition of extracellular matrix and crosslinked proteins, in particular collagen and elastin, leading to tissue stiffening and disrupted organ function." (PMID 30536539, 2019). "Age-associated lung tissue structural changes are characterized by enlarged alveoli, damaged alveolar walls, decreased gas exchange surface area, increased airway obstruction or occlusion, decreased pulmonary vascular density, deepened fibrosis, and decreased elastin content." (PMID 33648583, 2021). "Our data suggests the elastin-signature surrounding the alveoli in a staggered distribution, broken at intervals in 56Mn treated samples as early as six hours is an additional predictive indicator of radiation induced elastin fibrosis, which occurred in a local dose dependent manner." (PMID 32586004, 2020). "Using a collagen/elastin matrix routinely used under split‐thickness autografts in burn patients, we developed an in vitro fibrosis model to study the specific interaction between EC and dermal fibroblasts or ASC, without interference of other cell types present in the skin." (PMID 29345319, 2018). "Fibrosis is characterized by an increased accumulation of extracellular matrix (ECM) proteins such as collagen and elastin." (PMID 41714729, 2026). "In our findings, the suppression of ALKBH5 promoted the expression of COL3A1, COL1A1 and ELN, and these increased ECM components were subsequently secreted and deposited within the dermis, culminating in dermal fibrosis and scar hyperplasia." (PMID 39233335, 2024). "Fibrosis is defined as the pathological progress of excessive extracellular matrix (ECM), such as collagen, fibronectin, and elastin deposition, as the regenerative capacity of cells cannot satisfy the dynamic repair of chronic damage." (PMID 34594474, 2021). "Lysyl oxidase (LOX) fulfills a critical function in vascular fibrosis and extracellular matrix (ECM) remodeling by catalyzing the oxidation of lysine residues in collagen and elastin, thereby facilitating ECM cross-linking and contributing to vascular wall stiffening." (PMID 40661776, 2025).
Hyperglycemia (16 papers, 2010 to 2025). An increased concentration of glucose in the blood. "The double mutant mice exhibited hyperglycemia on control chow compared to WT mice, mice with elastin insufficiency alone, or mice with ApoE deficiency alone." (PMID 26167199, 2014). "However, elastin insufficiency coupled with ApoE deficiency (Eln+/−;ApoE−/−) was associated with hyperglycemia." (PMID 26167199, 2014). "In the medial layer of the aorta, hyperglycemia promotes advanced glycation end-product formation and ROS production, resulting in elastin fragmentation, collagen deposition, and cross-linking of elastin and collagen, thereby accelerating vascular stiffening." (PMID 40471971, 2025). "Hyperglycaemia induced by chronic intravenous injection of elastin-derived peptides was mitigated by DANA through the improvement of insulin sensitivity." (PMID 32251344, 2020). "The main mechanism of hyperglycemia affecting arterial stiffness is the generation and formation of AGEs, whose biochemical process may involve the glycosylation of vessel walls, subsequent crosslinking of collagen molecules, loss of collagen elasticity, and thinning of elastin fibers." (PMID 31052480, 2019). "Hyperglycemia has been observed in animals of the VitD/VitD group, and it induces glycosylation and degradation of elastin." (PMID 29850540, 2018). "The hyperglycemia-induced advanced glycation leads to cross-linking of elastin and collagen in the extracellular matrix within abdominal aorta wall." (PMID 28326193, 2017). "Prior animal studies have shown that hyperglycemia and insulin resistance lead to increased collagen deposition relatively early in disease progression while elastin may decline." (PMID 41149633, 2025). "Hyperglycemia may increase the reaction between glucose and proteins, promoting the cross-linking of collagen, elastin and other molecules, known as AGE, which could produce collagen deposits, tissue inflammation, and fibrosis within the vessel wall." (PMID 36443820, 2022). "Hyperglycaemia has been associated with increased PWV, which may be partly due to the accumulation of AGEs in elastin resulting in fracture of elastin and consequently stiffer arteries." (PMID 25940643, 2015). "The present study shows that hyperglycemia per se does not affect the expression of collagen or proteins important for collagen assembly, nor the elastin content in injured arteries." (PMID 29760458, 2018).
thoracic aortic aneurysm (16 papers, 2017 to 2026). An aneurysm formed in the wall of the proximal portion of the descending aorta proceeding from the arch of the aorta. "The mutation is accompanied by the onset of increased cytokine production, pro-inflammatory leukocytes, and elevated expression levels of MMPs-all of which drive elastin degradation and are classically associated with thoracic aortic aneurysm development." (PMID 42074482, 2026). "First, thoracic aortic aneurysm microcalcification is indicative of mild or moderate disease where the elastin is still largely intact and may represent a lower risk stage in the disease that could be initially managed conservatively and monitored over time." (PMID 35770666, 2022). "Fibrillogenesis involves the assembly of ECM proteins, such as collagen and elastin, which is critical for vascular integrity and is frequently disrupted in thoracic aortic aneurysms." (PMID 40650310, 2025). "Indeed, previous studies on human thoracic aortic aneurysm samples have shown a strong association between increased miR-29-3p expression and the downregulation of several ECM components, including COLLs and ELN." (PMID 39767655, 2024). "Visualizing aortic elastin and inflammation by ESMA and 18F-fluorodeoxyglucose positron emission tomography imaging, respectively, is an emerging technique for identifying high-risk inherited aortopathies that needs validation in human thoracic aortic aneurysms." (PMID 32392100, 2020). "Glycosaminoglycans (GAGs) pooling has long been considered as one of the histopathological characteristics defining thoracic aortic aneurysm (TAA) together with smooth muscle cells (SMCs) apoptosis and elastin fibers degradation." (PMID 35548440, 2022).
autosomal dominant cutis laxa (15 papers, 2012 to 2026). Autosomal dominant cutis laxa (ADCL) is a connective tissue disorder characterized by wrinkled, redundant and sagging inelastic skin associated in some cases with internal organ involvement. "Truncating variants in exons 1-29 typically produce non-syndromic SVAS through elastin haploinsufficiency, whereas C-terminal variants are linked to autosomal dominant cutis laxa." (PMID 41695747, 2026). "Autosomal Dominant Cutis Laxa is caused by a mutation in the ELN, FBLN5, or ALDH18A1 genes." (PMID 39480826, 2024). "Elastin gene mutations predominate as the cause of autosomal dominant cutis laxa (OMIM 123700)." (PMID 30704477, 2019). "Rare mutations in ELN, the gene coding for tropoelastin, cause autosomal dominant Cutis Laxa (ADCL), which is a condition that is associated with aortic dilatation and rupture in approximately 30–50% of patients." (PMID 33514025, 2021). "AOC3 (amine oxidase copper containing 3) was implicated by causal genes ELN and FBLN5 in age related macular degeneration which typically develops post-middle age, but it has previously been associated with Autosomal Dominant Cutis Laxa." (PMID 39480826, 2024). "In contrast, frameshift mutations at the 3’ terminus that result in a C-terminally elongated and secreted elastin protein have been identified in autosomal dominant cutis laxa (ADCL, OMIM #123700)." (PMID 23442826, 2013). "Similarly, in a study of 8 autosomal dominant cutis laxa patients, serum MMP-2 and 9 were significantly upregulated compared to normal levels suggesting systemic elastin degradation in autosomal dominant cutis laxa is due to protease dysregulation." (PMID 37001705, 2023).
Insulin resistance (15 papers, 2014 to 2026). Increased resistance towards insulin, that is, diminished effectiveness of insulin in reducing blood glucose levels. "Elastin degradation products (EDPs) have been associated with insulin resistance in preclinical studies, which is a property that can be reversed using the proteoglycan chondroitin sulfate, supporting a complex interplay between components of the ECM." (PMID 41149633, 2025). "Secondly, insulin resistance has been linked to heightened activity of MMPs, especially MMP‐2 and MMP‐9, which break down elastin and collagen in the aortic extracellular matrix, resulting in structural weakening and increased risk of dilation." (PMID 41499559, 2026). "Inhibition of FOXO1 activity by AS1842856 in insulin resistance conditions (palmitate + glucose) increased elastin and decreased MMP-9 expression compared to palmitate and glucose alone." (PMID 41049496, 2025). "Insulin resistance would result in a decrease in elastin fibers, reducing the stretch and flexibility of the aorta and leading to changes in aortic tortuosity and dilatation." (PMID 40594910, 2025). "Recently, a link has also been established between insulin resistance and the expression of neutrophil elastase (NE) or cathepsin S; this condition aggravates the fragmentation of elastin." (PMID 41049496, 2025). "Of note, insulin resistance has been linked to the abnormal expression of neutrophil elastase, a key enzyme for elastin fragmentation; in turn, EDPs have been involved in the development of insulin resistance in mice by a peroxisome proliferator-activated receptor-γ (PPARγ)-dependent pathway." (PMID 34439505, 2021). "Third, treating mice, which are both deficient in ApoE and display endothelium-specific insulin resistance, with the Nox2-specific inhibitor gp91dstat reduced superoxide generation and deposition of lipid in the thoraco-abdominal aorta without elastin fragmentation or increasing ICAM-1 expression." (PMID 32401607, 2020).
pulmonary hypertension (15 papers, 2014 to 2026). Increased pressure within the pulmonary circulation due to lung or heart disorder. "Extracellular matrix remodeling in the pulmonary arterial wall, manifested by dysregulated genes implicated in elastin degradation, precedes the onset of pulmonary hypertension." (PMID 37479718, 2023). "Preclinical studies have also supported the link between decreased WSS and vascular remodeling in the pulmonary circulation; for instance, reduced main pulmonary artery (MPA) WSS has been associated with increased collagen and elastin content in a rat model of pulmonary hypertension." (PMID 41243456, 2025). "In addition to the pulmonary artery stenosis seen in elastin deficiencies in humans, elastin deficiency has also been linked to smaller pulmonary arteries and pulmonary hypertension in a mouse model." (PMID 35229725, 2022). "Here, the authors show that elastin stabilization improves arterial biomechanics and attenuates pulmonary hypertension." (PMID 37479718, 2023). "Additional studies are warranted to evaluate the effects of surfactant and MSCs on pulmonary hypertension and collagen to elastin ratio in hyperoxia-induced lung injury." (PMID 33933128, 2021). "Accumulation of ECM proteins such as collagen, elastin, and fibronectin leads to thickening of pulmonary blood vessels, likely contributing to pulmonary hypertension." (PMID 24722050, 2014). "In addition, sildenafil (Viagra), another vasodilator used to treat impotence and pulmonary hypertension, aggravated elastin degeneration and experimental AAA progression by dysregulating cyclic guanosine monophosphate and contractile signaling in vascular smooth muscle cells." (PMID 37383707, 2023). "Lacking one elastin allele (Eln+/−) neonatal pulmonary capillary deficiency may cause pulmonary hypertension in adulthood." (PMID 35958401, 2022). "Ctss is a potent protease cleaving elastin in the arterial wall, and upregulation of CTSS has been observed in lung tissue from human patients with pulmonary arterial hypertension." (PMID 37660920, 2023). "The observed reduction in pPTT among high-altitude dwellers without pulmonary hypertension suggests adaptive vascular changes-likely mediated by hypoxia-driven arterial remodeling and elastin degradation." (PMID 42187508, 2026).
chronic kidney disease (14 papers, 2014 to 2025). Impairment of the renal function secondary to chronic kidney damage persisting for three or more months. "In a mixed chronic renal disease/apo E deficiency mouse model, a high cholesterol diet produced high-level cathepsin S protein expression and increased degradation of elastin fibers." (PMID 35453881, 2022). "As aging is also associated with high prevalence of chronic kidney disease, we sought to determine whether elastin haploinsufficiency predisposes Eln+/− mice to accelerated decline in kidney function with age." (PMID 37179824, 2023). "In addition, medial layer ossification might cause elastin degradation, extracellular matrix remodeling events, and increased phosphate in the blood, resulting in chronic kidney disease (CKD), hypertension, and T2DM." (PMID 36105908, 2022). "A similar suggestion was previously made in a model of chronic renal disease using ApoE−/− CatS-deficient or ApoE−/− mice treated with specific CatS inhibitors, where these mice showed a significantly reduced vascular calcification associated with fewer aortic elastin breaks." (PMID 31273243, 2019). "Chronic kidney disease is known to be involved in the degradation of elastin in the arterial wall and, as a result, in its stiffening." (PMID 38541930, 2024). "Unfortunately, treatment of CKD and end stage renal disease via hemodialysis results in even greater pentosidine and calcium deposits on medial aortic elastin which increase over time." (PMID 37001705, 2023). "Patients with end stage renal disease have more pentosidine and malondialdehyde adducts than those with early disease suggesting that elastin is modified by both glycoxidation as well as lipid peroxidation as the disease progresses." (PMID 37001705, 2023). "In patients with end-stage renal disease, immunostained pentosidine -a major glycoxidation product- was observed along the elastin fibers in aortic media." (PMID 28141808, 2017). "Dysregulation of normal anticalcification factors and elastin degradation represent a pattern of vascular injury existing in patients with end-stage renal diseases." (PMID 24949484, 2014). "However, medial elastin-specific calcification is a prevalent complication in patients and animal models with chronic kidney disease." (PMID 28164126, 2017). "The modification of elastin in the processes of glycoxidation and lipid peroxidation could lead to vascular lesions exaggeration in patients with end-stage renal disease." (PMID 26885251, 2016). "In addition, elastin is also affected by glycosylation and carbamylation which may exacerbate the progression of chronic kidney diseases by modulating the hardness of elastin." (PMID 34917605, 2021).
asthma (13 papers, 2011 to 2025). "MMPs are a family of enzymes involved in the remodeling of extracellular matrix components, such as collagens and elastin, which play a crucial role in asthma." (PMID 38275403, 2024). "In corroboration with other studies, they found that asthma-derived eosinophils caused an upregulation in the ECM proteins collagen I, collagen III, fibronectin, and elastin in MRC-5 fibroblasts." (PMID 36911735, 2023). "Airway remodelling is a feature of asthma including fragmentation of elastic fibres observed in the superficial elastin network of the airway wall." (PMID 21699692, 2011). "Targeted inhibition of proline biosynthesis in the lung extracellular matrix may mitigate aberrant elastin accumulation observed in fatal asthma and airway remodeling due to increased collagen deposition in uncontrolled, corticosteroid-resistant asthma." (PMID 37293566, 2023). "In summary, various studies have shown that asthma-derived eosinophils interact with fibroblasts to stimulate the over production of ECM proteins (e.g., collagen I, collagen II, fibronectin, elastin, α-SMA) and profibrotic cytokines such as TGF-β that are implicated in asthma fibrosis." (PMID 36911735, 2023). "Asthma significantly enhanced elastin fragmentation in the aortic wall only in FcɛR1+/+ mice." (PMID 31440377, 2019). "Additionally, fragmentation and a decreased amount of elastic fibres have been observed in the superficial elastin network of central airways in fatal asthma." (PMID 21699692, 2011). "Other studies showed that the gene and/or protein expression of collagen I, fibronectin, versican, elastin, tenascin C, periostin, and vimentin was increased in ASMC and PF in asthma studies, including in vivo, ex vivo, in vitro, and animal model studies." (PMID 35456903, 2022). "431–443) used nonlinear optical microscopy (NLOM) to assess the biochemical and structural features of collagen and elastin in nontransplantable donor lungs from individuals with and without asthma." (PMID 30985216, 2019). "As one of the most important signatures of human and animal AAA, elastin fragmentation in the aortic wall was examined in AAA mice with or without asthma." (PMID 31440377, 2019). "However, the similar changes in the airways, only in vivo, were shown in a study where several ECM proteins such as collagen I, fibronectin, elastin as well as matrix metalloproteinases (MMP) 9 and 12 were increased in large and small airways during an autopsy in fatal asthma patients." (PMID 32155894, 2020). "However, unlike patients with asthma or COPD, healthy older individuals do not have significant airway inflammation or changes in collagen and elastin content." (PMID 40709067, 2025).